OPA1 (OPA1 mitochondrial dynamin like GTPase)
Diseases named in the same sentence as OPA1 in open-access papers (continued):
Sharing a sentence is not in itself a finding about the gene and the disease.
autosomal dominant optic atrophy (continued). "Both proteins interact with OPA1, with nonsynonymous OPA1 mutations causing the unrelated Mendelian disease Autosomal Dominant Optic Atrophy (ADOA) by triggering mitochondrial-led retinal ganglia cell apoptosis." (PMID 18846214, 2008). "Variants in OPA1 are a major cause of autosomal dominant optic atrophy (DOA)." (PMID 41898875, 2026). "A similar mechanism involving CaN has been reported in mouse and nematode models of Autosomal Dominant Optic Atrophy (ADOA), characterized by loss-of-function mutations in the fusion-related Mitochondrial Dynamin Like GTPase optic atrophy 1 (OPA1)." (PMID 39911695, 2025). "Disruptions in OPA1 function have been implicated in various diseases, including cardiomyopathy, Behr Syndrome, autosomal dominant optic atrophy (DOA), metabolic stroke, syndromic parkinsonism, and dementia." (PMID 40437978, 2025). "In OPA1-related dominant optic atrophy patients, the metabolic profile showed an impairment of the purine metabolism, including significant differences in xanthine, hypoxanthine, and inosine concentrations." (PMID 40924311, 2025). "Mutations in OPA1 have been implicated in various diseases, with the most common being autosomal dominant optic atrophy (ADOA) and dominant optic atrophy plus syndrome (DOA+), the latter of which is characterized by multisystem neurodegeneration including myopathy, ataxia, and dementia." (PMID 40354372, 2025). "Mutations in genes associated with mitochondrial fusion, including OPA1, AFG3L2, and MIEF1, lead to autosomal dominant optic atrophies (DOAs), specifically optic atrophy 1 (OPA1), optic atrophy 12 (OPA12), and optic atrophy 14 (OPA14), respectively." (PMID 39201313, 2024). "The Autosomal Dominant Optic Atrophy diagnosis has been confirmed by the OPA1 heterozygous deletion identification." (PMID 38641846, 2024). "Dominant optic atrophy (DOA) is one of the most prevalent forms of hereditary optic neuropathies and is mainly caused by heterozygous variants in OPA1, encoding a mitochondrial dynamin-related large GTPase." (PMID 38334784, 2024). "Autosomal dominant optic atrophy (ADOA) is a rare progressive disease mainly caused by mutations in OPA1, a nuclear gene encoding for a mitochondrial protein that plays an essential role in mitochondrial dynamics, cell survival, oxidative phosphorylation, and mtDNA maintenance." (PMID 39000346, 2024). "Patients with mutated OPA1 develop autosomal dominant optic atrophy (ADOA) and neutrophils from these patients have a reduced ability for extracellular DNA released and impaired ability for pathogen killing due to impaired complex I activity, and limited NAD+ for glycolytic ATP production." (PMID 38259490, 2023). "Human OPA1 mutations cause autosomal dominant optic atrophy (ADOA) and ADOA plus, depending on the severity of OPA1 defects." (PMID 37872238, 2023). "Autosomal dominant optic atrophy (DOA) served as a model to understand the function of OPA1 and investigate the consequences of fusion defects." (PMID 37047239, 2023). "In addition, the occurrence of mutations in the gene encoding OPA1 are associated with autosomal dominant optic atrophy (ADOA) and ADOA+ syndromes, characterized by visual loss and in the latter case also by more widespread neurological symptoms." (PMID 36307526, 2023). "Autosomal dominant optic atrophy (OPA1) is the mammalian ortholog of yeast Mgm1p, and it is associated with mitochondrial fusion." (PMID 37627290, 2023). "Another therapeutic approach that is being evaluated in individuals with dominant optic atrophy (DOA), including those with OPA1 pathogenic variants, is autologous bone-marrow-derived stem cells (BMSC)." (PMID 35736332, 2022). "The purpose of the study was to evaluate vision‐related quality of life and visual ability in patients with OPA1 autosomal dominant optic atrophy (ADOA)." (PMID 35146926, 2022).
autosomal dominant optic atrophy (continued). "Loss-of-function mutations in MFN2 and OPA1 genes cause two neurodegenerative diseases, Charcot–Marie–Tooth type 2A (CMT2A) and dominant optic atrophy (DOA), respectively." (PMID 33078210, 2021). "Interestingly, it is observed that OPA1 gene mutations, resulting in autosomal dominant optic atrophy (ADOA), are correlated with multiple sclerosis-like disorders." (PMID 33379309, 2020). "Mutations in OPA1 and MFN2 genes cause autosomal dominant optic atrophy (DOA); mutations in WFS1 and CISD2 can cause Wolfram syndrome, while Leber's hereditary optic neuropathy (LHON) is associated with mutations in mitochondrial ND1, ND4, and ND6 genes." (PMID 32352005, 2020). "In autosomal dominant optic atrophy (ADOA), caused by mutations in the mitochondrial cristae biogenesis and fusion protein optic atrophy 1 (Opa1), retinal ganglion cell (RGC) dysfunction and visual loss occur by unknown mechanisms." (PMID 32788597, 2020). "Autosomal dominant optic atrophy (ADOA) is an untreatable disease caused by OPA1 mutations." (PMID 32788597, 2020). "The commonest form of inherited optic neuropathy, called dominant optic atrophy (DOA) or optic atrophy-1 (OPA1; MIM# 165500), was initially described by Kjer." (PMID 31500643, 2019). "These range from the inability to survive past mid-gestation in MFN1, MFN2, OPA1, or DRP-1 deficient mice, to neurodegenerative diseases such as Charcot-Marie-Tooth syndrome and dominant optic atrophy caused by mutations in MFN2 and OPA1." (PMID 31225513, 2019). "These first gene therapy results established the hints that OPA1 expression in retinal ganglion cells can be an effective solution to treat dominant optic atrophy." (PMID 29410463, 2018). "Dominant optic atrophy (DOA) is one of the most frequent forms of these diseases, and is mainly related to dominant OPA1 mutations." (PMID 29410463, 2018). "It is noteworthy that mutations in human OPA1, a direct target of human NRF1, are the cause of autosomal dominant optic atrophy, which leads to retinal ganglion cell death." (PMID 30333037, 2018). "Mutations in Mfn2 cause Charcot-Marie-Tooth type 2A (CMT2A), a peripheral neuropathy affecting sensory and motor neurons, while mutations in OPA1 are the primary cause of autosomal dominant optic atrophy (DOA), a degeneration of retinal ganglia cells that results in atrophy of the optic nerve." (PMID 26903809, 2016). "Mutations in the fusion genes OPA1 and MFN2 have been associated with dominant optic atrophy and CMT Type 2A, respectively, but the reasons for these genotype–phenotype correlations have remained an enduring mystery." (PMID 27390132, 2016). "Dominant optic atrophy (DOA) is the most common form of autosomal inherited optic neuropathy, mainly caused by mutations in the optic atrophy 1 (OPA1) gene." (PMID 23401657, 2013). "Indeed, we analyzed some of these patients and identified mutations in the OPA1 gene, suggesting that these patients should be classified as autosomal dominant optic atrophy (ADOA; authors' unpublished data)." (PMID 22110754, 2011). "Mutations in OPA1 are a principle cause of autosomal dominant optic atrophy (DOA)." (PMID 21203403, 2010). "Autosomal dominant optic atrophy (ADOA), a form of progressive bilateral blindness due to loss of retinal ganglion cells and optic nerve deterioration, arises predominantly from mutations in the nuclear gene for the mitochondrial GTPase, OPA1." (PMID 18783614, 2008). "For example, several neurological diseases (e.g. Charcot-Marie-Tooth, CMT; autosomal dominant optic atrophy, DOA) are associated with mutations in proteins that control mitochondrial dynamics and morphology like mitofusin-2 and OPA1." (PMID 18713454, 2008). "Interestingly, past studies have implicated BNIP3 in the progression of Dominant optic atrophy (DOA), a disease that arises due to mutations in OPA1, an important fusion protein in the mitochondrial dynamics." (PMID 38030595, 2024).
autosomal dominant optic atrophy (continued). "Recognizing these constraints, healthcare professionals must acknowledge these limitations and consistently search for OPA1 variants/deletions in Autosomal Dominant Optic Atrophy (ADOA) patients with negative sequencing results." (PMID 38641846, 2024). "Dominant Optic Atrophy (DOA) constitutes one of the most common inherited optic neuropathies and pathogenic OPA1 variants have been identified in ~ 60% of these families whilst pathogenic variants in TWNK clinically manifests as autosomal dominant progressive external ophthalmoplegia (adPEO)." (PMID 39272026, 2024). "Genetic analysis for Leber’s hereditary optic atrophy and autosomal dominant optic atrophy (OPA1) showed no pathological variants." (PMID 36653599, 2023). "Alteration in OPA1 expression in BBSOAS models is particularly interesting considering that OPA1 haploinsufficiency is the major genetic pathological mechanism of autosomal-dominant optic atrophy in humans and that optic atrophy in BBSAOS patients is among the most common clinical features." (PMID 37260288, 2023). "Interestingly, Mgm1 is the yeast counterpart of the human OPA1 gene, which when mutated, has implications in dominant optic atrophy (DOA), a form of neurodegenerative disease." (PMID 38011208, 2023). "Thus, mitochondrial failure causes several types of optic neuropathy, such as Leber’s hereditary optic neuropathy (caused by point mutations in the mitochondrial DNA) and autosomal dominant optic atrophy (ADOA; caused by mutations in the OPA1 gene, which is involved in mitochondrial fusion)." (PMID 36901786, 2023). "One recent study found that three members of a family had autosomal dominant optic atrophy caused by OPA1 mutations and two of them developed nonsyndromic PD." (PMID 36611869, 2022). "The Opa1+/− mouse model reproduces the autosomal dominant optic atrophy (ADOA) syndrome in humans." (PMID 35739974, 2022). "Homozygous Opa1 mutant mice die in utero during embryogenesis, but heterozygous Opa1 mutants display the main features of human dominant optic atrophy including abnormal mitochondrial morphology, disorganized cristae structure, mitochondrial dysfunction and mtDNA instability." (PMID 36158192, 2022). "SSBP1- and OPA1-related dominant optic atrophies share common characteristics, including the early onset before the age of 10 years, bilateral and symmetrical mild to severe visual loss, and large intra- and inter-familial variability, including asymptomatic carriers." (PMID 34548540, 2021). "The WES findings for two patients (patient 10 and patient 6) showed disease-causing variants in OPA1 and SURF1, respectively, and these findings were correlated with their corresponding syndromic presentations of autosomal dominant optic atrophy (ADOA) and Leigh syndrome." (PMID 32907636, 2020). "Idebenone has also been used to treat OPA1-dependent Dominant Optic Atrophy." (PMID 33187380, 2020). "In patients carrying OPA1 mutations and having clinical signs of autosomal dominant optic atrophy, memory functions have not been systematically reported." (PMID 33094281, 2020). "Autosomal dominant optic atrophy (ADOA, OMIM 165500), an inherited optic neuropathy that leads to retinal ganglion cell degeneration and reduced visual acuity during the early decades of life, is mainly associated with mutations in the OPA1 gene." (PMID 19325939, 2009). "Mammalian cells transfected with Opa1 siRNA are more sensitive to apoptosis inducing agents, but there is also evidence that patients with dominant optic atrophy have reduced levels of ATP, which could trigger retinal ganglion cell degeneration." (PMID 18454199, 2008). "Disruptions in these processes, often caused by MFN2 or OPA1 mutations, are linked to neurodegenerative diseases like Charcot-Marie-Tooth disease type 2A (CMT2A) and autosomal dominant optic atrophy (ADOA)." (PMID 40149969, 2025).
autosomal dominant optic atrophy (continued). "Autosomal dominant optic atrophy (DOA) is a progressive form of blindness caused by degeneration of retinal ganglion cells and their axons, mainly caused by mutations in the OPA1 mitochondrial dynamin like GTPase (OPA1) gene." (PMID 39177028, 2024). "Pathogenic variants of the OPA1 gene (OMIM:605290) are the most common cause of autosomal dominant optic atrophy, and patients may present with or without hearing loss." (PMID 35884828, 2022). "OPA1 mutants are responsible for the autosomal dominant optic atrophy-1 (ADOA), a neuro-ophthalmic condition primarily characterized by impairment of visual acuity and generalized color-vision deficits." (PMID 33924849, 2021). "Furthermore, 15/19 (78.9%) of the positive genetic test results detected in the nuclear genes were in OPA1. these results support that most cases of inherited optic atrophy can be attributed largely to dominant optic atrophy resulting from genetic changes in OPA1 (50–80%)." (PMID 31765440, 2019). "Neurodegenerative diseases such as Charcot–Marie–Tooth 2A (CMT2A) and dominant optic atrophy (DOA) manifest with degeneration of sensory and motor nerves and optic nerve as a direct consequence of mutations in genes encoding mitochondrial fusion proteins Mfn2 and OPA1, respectively." (PMID 26921061, 2016). "OPA1 was first identified through its involvement in the neurodegenerative disease known as autosomal dominant optic atrophy (ADOA)." (PMID 22203837, 2012). "Remarkably, a recent gene expression profile study has shown that the optic atrophy 1 (OPA1) gene, which is related to autosomal dominant optic atrophy (ADOA), the most common form of hereditary optic neuropathy, is downregulated in some LHON patients." (PMID 21347331, 2011). "Because most of pathogenic mutations in OPA1 are expected to produce a truncated non-functional OPA1 protein, it has been suggested that haploinsufficiency is a major pathomechanism in OPA1-associated autosomal dominant optic atrophy." (PMID 20664796, 2010). "However, OPA1 is known for its relevance in autosomal dominant optic atrophy (ADOA), which is the most common form of hereditary optic neuropathy." (PMID 35457050, 2022). "Mutations in the optic atrophy type 1 gene (OPA1; OMIM: 605290) cause autosomal dominant optic atrophy (ADOA; OMIM: 165500), which is characterized by slowly progressive bilateral loss of visual acuity, centrocecal visual field defects, and color vision disturbances." (PMID 34853716, 2021). "The thinning of the RNFL layer was segmental in nature compared with other inherited optic neuropathies, such as OPA1-related and WFS1-related dominant optic atrophy, in which more generalized RNFL thinning has been reported in all segments." (PMID 34466801, 2021). "Another ANSD with good results on CI is a syndromic ANSD accompanied by autosomal dominant optic atrophy (ADOA, OMIM #165500) due to OPA1 variations." (PMID 29184165, 2017). "Recently, mutations in OPA1 and MFN2 have been described in patients with autosomal dominant optic atrophy (ADOA) and multisystem clinical involvement (including progressive external ophthalmoplegia (PEO)) who harbored mitochondrial DNA (mtDNA) deletions in skeletal muscle." (PMID 23781337, 2013). "Autosomal dominant optic atrophy (ADOA; OMIM 165500) is caused by a mutation in the OPA1 gene." (PMID 24024178, 2013). "Homozygous OPA1 mutant mice do not survive past embryonic development, while heterozygous OPA1 mutants exhibit key features of human dominant optic atrophy." (PMID 40703715, 2025). "Finally, PARL is a mitochondrial protease, which cleaves, among others, OPA1 and PINK1, genes responsible for dominant optic atrophy and familial Parkinson’s disease." (PMID 24369379, 2014). "To verify the relevance of OPA1 for DNA release and NET formation in primary human neutrophils, we isolated blood neutrophils from two patients of the same family (father and son), both suffering from autosomal dominant optic atrophy disease (ADOA)." (PMID 30054480, 2018).
optic atrophy (126 papers, 2007 to 2025). A disorder characterized by loss of optic nerve fibers. "The yeast/human protein chimera of Mmg1p/OPA1 was used to study the effects of missense mutations associated with optic atrophy." (PMID 40076772, 2025). "For example, mutations in human genes MFN2 and OPA1, involved in mitochondrial fusion, lead to abnormal mitochondrial morphology and are associated with Charcot–Marie–Tooth disease and optic atrophy, respectively." (PMID 40076772, 2025). "In these cases, the causative mutations (mtDNA complex I genes in LHON or OPA1 and a few other optic atrophy genes in DOA) primarily affect cellular energy supply and survival specifically in RGCs." (PMID 40332750, 2025). "Regarding the in-house cohort, 85.06% (131/154) of families manifested non-syndromic optic atrophy, with families harbouring OPA1 variants representing the largest fraction (80 families) compared with other genes." (PMID 39423307, 2025). "Genetic variant associated with ADOA include: OPA1 gene, heterozygous, nonsense, NM_130837.2:c.2383C > T/(p.Gln795∗), pathogenic, optic atrophy, autosomal dominant." (PMID 40417638, 2025). "In the third generation, an affected male (the father in this family), diagnosed with optic atrophy due to OPA1 c.2383C > T variant, married a woman (the mother) carrying the LHON MT-ND4 m.11778G > A variant." (PMID 40417638, 2025). "Heterozygous mutations in the gene encoding OPA1, a protein critical for normal mitochondrial fusion, underlie dominant optic atrophy." (PMID 38324746, 2024). "Although the main clinical manifestation associated with monoallelic OPA1 defect is optic atrophy, about 20%–30% of patients develop additional extraocular manifestations including a plethora of neurological features." (PMID 39233737, 2024). "Optic atrophy is a characteristic feature of OPA1-associated DOA; however, multisystem symptoms have been reported in up to 20% of OPA1 mutation carriers." (PMID 39177028, 2024). "A novel CACNA1F variant was identified in a young male patient, originally diagnosed with optic atrophy in which the MRI was unremarkable and the presence of mutations in the OPA1 gene was excluded." (PMID 39564550, 2024). "In case of OPA1 mutations, it was observed that optic atrophy and unilateral hearing loss presentations were present in 62% of cases." (PMID 39274256, 2024). "In a second family with CNM, a homozygous pathogenic variant was found in the OPA1 gene, which encodes a mitochondrial protein previously linked to optic atrophy." (PMID 38982518, 2024). "Optic atrophy type 1 (Opa1) is a gene known for optic atrophy, in which 11 out of 19 known mutations are also associated with SNHL at various ages, from childhood to 30 years old." (PMID 39204103, 2024). "In this study, we demonstrate early mitochondrial changes in the retina and the prelaminar ON of mouse models of hereditary optic atrophy carrying mutations in the Opa1 and MT-Nd6 genes." (PMID 39659974, 2024). "DOA+ syndromes, for example, have been described as optic atrophy seen variably with deafness, ataxia, neuropathy, myopathy and/or progressive external ophthalmoplegia associated with OPA1 pathological variants." (PMID 38397177, 2024). "Although haploinsufficient-related mutations in OPA1 lead to optic atrophy, dominant gain-of-function mutations in OPA1 cause more severe phenotypes of optic atrophy, often concomitant with deafness, axonal neuropathy, ataxia, and/or myopathy." (PMID 36977595, 2023). "The reported yield of nuclear and mitochondrial DNA sequencing in bilateral optic atrophy is around 20% and includes pathogenic variants in the OPA1, mtDNA genes, or rarely WFS1, MFN2, POLG, ACO2, and DNAJC30 genes." (PMID 36294366, 2022).